CDH6 (cadherin 6)
Diseases named in the same sentence as CDH6 in open-access papers (continued):
Sharing a sentence is not in itself a finding about the gene and the disease.
cancer (continued). "Furthermore, CDH6 exhibited both positive and negative correlations with markers of Th cells, enhanced T cells, cancer-associated fibroblasts, and M1 and M2 macrophages." (PMID 35938030, 2022). "However, the role of CDH6 in cancer metastasis is largely unclear." (PMID 33715292, 2021). "Several cadherins including CDH6 were identified as RGD motif-containing proteins, which can function as ligands to activate metastasis-associated integrins, including β1-containing integrins such as α2β1, and promote cancer cell proliferation, migration and invasion 67-69." (PMID 33204327, 2020). "We report the preclinical characterization of CUSP06, a novel CDH6-targeted ADC, which supports the clinical development of CUSP06 in multiple CDH6-expressing human cancers." (PMID 40871070, 2025). "Clinical data from various cancer types were analyzed to reveal relationships among YAP1, OCT4, and CDH6 in MSC--involved tumorigenicity." (PMID 35356283, 2022). "We evaluated the effectiveness of CDH6 in predicting drug responses using data from the PRISM and Cancer Therapeutics Response Portal (CTRP) databases." (PMID 35938030, 2022). "CDH6 is an EMT biomarker often highly expressed in solid tumors and enhances cancer invasiveness and metastasis [ (Casal and Bartolomé, 2019)." (PMID 35356283, 2022). "We evaluated the strong correlation of CDH6, YAP1, and OCT4 expression within solid tumors by analyzing 56 clinical cancer cohorts from Oncomine and TCGA databases." (PMID 35356283, 2022). "The expression of CDH6, DPYSLE3, GJA1, IL15, and ACTA2 is also relevant to survival in many types of cancers, but its mechanism of action in CRC requires further study to explore its impact." (PMID 34211976, 2021). "CDH6, a class II Cadherin, induces EMT during embryonic development and shows abnormal reactivation in malignant tumors." (PMID 34281542, 2021). "In this review, we will discuss the structural and functional properties of cadherin 5 (CDH5), cadherin 6 (CDH6) and cadherin 17 (CDH17), as well as their pathological implications in cancer progression and metastasis." (PMID 31324051, 2019). "CDH6 which is a type 2 cadherin and an epithelial marker drives EMT during embryonic development and it is aberrantly re-activated in cancer." (PMID 28704482, 2017). "Of note, whereas the α2β1 integrin has a widespread expression, the αIIbβ3 integrin expression is limited to a select number of cell types, which also express CDH6 (as oligodendrocyte progenitors) or CDH5 (as late spermatids and lymphatic endothelial cells), or to several cancer types." (PMID 41039222, 2025). "However, earlier studies have reported that secreted GRS from macrophages bound to cadherin 6 (CDH6), and released phosphatase 2A (PP2A) to induce apoptosis in cancer cells by suppressing ERK signaling pathway." (PMID 36017335, 2022). "For total protein levels, CDH6 was highly expressed in ovarian (OVCAR3 and SKOV‐3) and renal (RCC4 and 786‐O) cancer cell lines except in CAKI‐1 and A‐2780, while CDH17 was expressed in all cell lines, with RCC4, 786‐O, and OVCAR3 exhibiting the highest amounts." (PMID 33715292, 2021). "Differential analysis on cancer reads of the KIRC against the other 8 PDX types revealed 1,181 DE genes (q< 0.05, BH adjusted), with the lowest q-value identified for POU3F3, SLC28A1, and CDH6 genes." (PMID 35079698, 2021). "Cadherin-6 (CDH6) and long noncoding RNA MEG3 have been respectively recognized as upstream and downstream targets of miR-223, whether these genes were involved in exosomal miR-223-mediated cancer progression remains to be further explored." (PMID 35578228, 2022).
tumor (40 papers, 2001 to 2025). "CDH6 strongly correlated with immunosuppressive cells, including Tregs, monocytes, macrophages, tumor-associated macrophages (TAMs), and MDSCs." (PMID 35938030, 2022). "CDH6 strongly correlated with immunosuppressive cells, including regulatory T cells, monocytes, macrophages, tumor-associated macrophages, and myeloid-derived suppressor cells." (PMID 35938030, 2022). "Through the bioinformatics analysis, this study not only identified a tumor suppressor gene of CCA, CDH6, which has been confirmed by relevant basic studies, but also found a tumor‐promoting oncogene, HPCAL1, which was associated with poor prognosis of CCA and was confirmed by our validation cohort." (PMID 35645147, 2023). "CDH6 was reported to be associated with tumor progression and poor prognosis of GC." (PMID 35719415, 2022). "In other malignancies, CDH6 was reportedly associated with tumor growth and a poor prognosis." (PMID 34530820, 2021). "Furthermore, it was reported that CDH6 could cause tumor cells to lose cellular polarity, further highlighting the potential for CDH6 as a target for antibody–drug conjugate (ADC) therapy development." (PMID 34530820, 2021). "The characteristic of limited expression in normal tissues, high expression in tumor tissues, and rapid internalization upon antibody binding makes CDH6 a well-suited antibody-drug conjugate (ADC) target." (PMID 40871070, 2025). "The characteristics of limited expression in normal tissues, high expression in tumor tissues, and rapid internalization upon antibody binding makes CDH6 an ideal ADC target." (PMID 40871070, 2025). "A single dose of 10 mg/kg CUSP06 significantly regressed the tumor growth in a CDH6-high, PARP inhibitor-resistant ovarian PDX model (LD1-1588, CDH6 H-score = 280) compared to isotype-ADC control (p < 0.05)." (PMID 40871070, 2025). "In vitro cell mixing experiments demonstrated CUSP06 possessed enhanced bystander effect compared to R-DXd, which is important for anti-tumor activity in CDH6-low or heterogeneous tumors." (PMID 40871070, 2025). "CDH6 expression positively correlated with the World Health Organization (WHO) tumor grade and negatively correlated with patient prognosis." (PMID 35938030, 2022). "Tumor immune infiltration abundance of macrophage also shown a significantly associated with CDH2 (r = 0.474, P = 3.59 × 10−22), CDH6 (r = 0.418, P = 4.20 × 10−17) and CDH10 (r = 0.492, P = 6.60 × 10−24) in GC tumor tissues." (PMID 34880371, 2021). "Putative tumour suppressor genes CDH6 and IGF2BP2 were two of the most significantly fold-decreased genes (p = 0.0003 and p = 5.71 × 10−5 respectively)." (PMID 30513694, 2018). "Further analyses are required in order to fully understand the functional relevance of CDH6 in the EMT program during tumor progression." (PMID 24069422, 2013). "As for the other mesenchymal markers, CDH6 expression was higher in tumor tissue (black circles) and LNMs than in normal tissue (baseline)." (PMID 24069422, 2013). "Both isoforms were expressed in all cell lines and more strongly expressed in tumor-derived cells than in Nthy.ori 3.1, as observed for the total CDH6." (PMID 24069422, 2013). "This is intriguing since our data would suggest that in a pathological setting such as tumor development, the CDH6 plays an opposite role." (PMID 24069422, 2013). "In vivo administration of GARS strongly suppresses tumour growth in a mouse model, accompanied by CDH6 induction and ERK activation." (PMID 23427196, 2013). "Our data also show that CDH6 expression is constitutively higher in tumor cells than in normal thyrocytes, both in vitro and in vivo." (PMID 24069422, 2013). "Macrophage-derived EVs have also been shown to transfer GARS1, which suppresses tumor growth by inducing M1 polarization, promoting macrophage phagocytosis via activation of the RAF-MEK-ERK pathway, and triggering tumor cell death through interaction with CDH6." (PMID 40317075, 2025).
tumor (continued). "The data indicated that CUSP06 of capable of killing not only the CDH6-expressing tumor cells, but also the CDH6-negative tumors cells likely via bystander killing effect and proximity near the CDH6-expressing cells in this heterogeneous CDH6-expressing PDX model." (PMID 40871070, 2025). "Besides, cadherin-6 was highly expressed in GC, and its high expression was correlated with tumor progression and poor prognosis of patients with GC." (PMID 36712590, 2023). "Tumor purity negatively correlated with CDH6 expression (R = 0.24; p = 0)." (PMID 35938030, 2022). "All these four prognostic genes were significant associated with dendritic cell Tumor immune infiltration abundance: CDH2 (r = 0.296, P = 5.84 × 10−9), CDH6 (r = 0.164, P = 1.49 × 10−3), CDH6 (r = − 0.105, P = 4.41 × 10−2) and CDH10 (r = 0.274, P = 7.78 × 10−8)." (PMID 34880371, 2021). "By analyzing the relationship between the prognostic CDH genes and the abundance of tumor immune infiltration, we found that expression level of CDH6 (r = 0.138, P = 7.82 × 10−3) and CDH7 (r = 0.104, P = 4.57 × 10−2) were significantly related to B cell infiltration in GC tumor tissues." (PMID 34880371, 2021). "Since CDHs have been found not only at the interface between tumor cells but also in bodily fluids (mainly in the blood), CDH6 could be readily detectable in a clinical setting." (PMID 34530820, 2021). "Intriguingly, CDH6-positive cells were localized preferentially at the invasion front of the tumor, strongly supporting the hypothesis that CDH6 is important in controlling cell motility and invasiveness in PTCs." (PMID 24069422, 2013). "Further functional data are required in order to support this hypothesis and to fully understand the function of CDH6 in the EMT program during tumor progression." (PMID 24069422, 2013). "As expected, CDH6 expression was clearly higher in tumor cells than in normal tissue." (PMID 24069422, 2013). "By contrast, CDH6-L is highly expressed and more abundant than the short form in tumor-derived cells, suggesting that the intracellular interactions of CDH6 could be functional to the role of this protein during tumor progression." (PMID 24069422, 2013). "Furthermore, the authors demonstrated that the potential BTC-related tumor suppressor CDH6 is a direct target of miR429, and that downregulation of CDH6 occurs stepwise during BTC progression (with BTC showing the lowest levels) and is associated with poor overall survival." (PMID 27941621, 2016). "This hypothesis is strongly supported by our observation that in human PTC samples, CDH6 expression is detectable mainly at the invasive front of the tumor, where tumor cells need to loosen their intracellular interaction to gain motility and invade the adjacent tissues." (PMID 24069422, 2013). "Our study shows for the first time that CDH6 expression is also elevated in RA FLS, which display many features of aggressive tumor cells, such as enhanced invasiveness and survival." (PMID 40877928, 2025). "The status of CDH6 promoter methylation, expression, and survival was investigated for the different WHO tumor grades." (PMID 35938030, 2022). "CDH6 is an EMT marker that is highly expressed in solid tumors and that facilitates tumor invasiveness and metastasis." (PMID 35938030, 2022). "The expression level of CDH2(r = 0.263, P = 3.54 × 10−7), CDH6 (r = 0.307, P = 2.04 × 10−9) and CDH10 (r = 0.33, P = 9.99 × 10−11) in GC tumor tissues were closely related to CD4 + T cell immune infiltration." (PMID 34880371, 2021). "The secreted GRS interacted with specific ERK-activated tumor cells through cadherin-6 (CDH6), thereby enhancing phosphatase 2A (PP2A) activity by releasing PP2A from CDH6 and reducing PP2A phosphorylation." (PMID 33330488, 2020).
tumor (continued). "The following marker genes were differentially expressed in the triphasic tumours relative to the blastemal tumours: PA (LHX1), RV/CSB/SSB (BMP2, CDH6, JAG1, PAPSS2), ePT and/or imHL (CIDEB, CLIC6, UNC5CL, VDR), and early DT/imHL (KCNJ1)." (PMID 29040332, 2017). "TCGA-A tumours showed higher expression of most group I/FTEC epithelial proteins such as KRT7, MSLN, CDH6, ASS1 and EPCAM, while TCGA-B tumours had higher expression of the group III/IOSE mesenchymal proteins ITGA5, HMOX1, SMTN and GJA1 (refs 7, 34)." (PMID 27561551, 2016). "CDH6 expression correlated with the ESTIMATE score and tumor purity." (PMID 35938030, 2022). "Cadherin-6, a marker and mediator of epithelial-mesenchymal transition (EMT), is also expressed by platelets and was recently shown to support contacts between platelets and tumor cells via homophilic and heterotypic interactions." (PMID 35565321, 2022). "Furthermore, we examined the correlation between CDH6 expression and the ESTIMATE score and tumor purity." (PMID 35938030, 2022). "Based on our expression data, it would be tempting to speculate that, unlike other mesenchymal markers widely expressed in the tumor tissues, CDH6 could be preferentially involved in the later phases of EMT more directly linked to invasiveness of the cells." (PMID 24069422, 2013). "However, the expression of CDH6 was not uniform within the tumor but was restricted to groups of cells." (PMID 24069422, 2013). "However, the fact that CDH6 levels increase in response to TGF-β as the N-CAD and in contrast with the downregulation of E-CAD suggests that this protein is involved in the Cadherins switch, favoring the rupture of the tight cell-cell junctions and increasing the motility of tumor cells." (PMID 24069422, 2013).
disorder of the brain (1 paper, 2020). "As AD is a disorder of the brain, we have validated that CSF levels of CDH6 are also associated with biomarkers of AD in CSF in an independent cohort." (PMID 32427856, 2020).
CDH6 also shares sentences with these, for which no sentence is quoted: breast carcinoma (6 papers); renal cell carcinoma (5); colorectal cancer (3); oral squamous cell carcinoma (3); Alzheimer disease (2); colon cancer (2); infection (2); vascular disorder (2); acute myeloid leukemia (1); adenoma (1); Anxiety (1); Aphasia (1); atherosclerosis (1); Autoimmunity (1); COVID-19 (1); endometrial cancer (1); epilepsy (1); gallstones (1); gastroesophageal junction adenocarcinoma (1); glomerular disease (1); head and neck squamous cell carcinoma (1); hearing loss (1); holoprosencephaly (1); kidney (1); lung carcinoma (1); metabolic syndrome (1); neurotoxicity (1); ocular hypertension (1); ovarian serous carcinoma (1); ovarian tumor (1).
A further 6 diseases each share a sentence with CDH6 in 1 paper.